IDI2 (isopentenyl-diphosphate delta isomerase 2)
Description:
Catalyzes the 1,3-allylic rearrangement of the homoallylic substrate isopentenyl (IPP) to its highly electrophilic allylic isomer, dimethylallyl diphosphate (DMAPP).
Synonyms: IPPI2
Tractability: PROTAC: ubiquitination databases record sites on it; its protein half-life has been measured.
Gene: Protein-coding gene on chromosome 10 (1,018,910 to 1,025,859, reverse strand). Ensembl gene ENSG00000148377.
Subcellular location: Peroxisome
Subcellular location (Human Protein Atlas): Vesicles
Pathways (Reactome):
Metabolism: Lanosterol biosynthesis
Gene Ontology:
Molecular function: isopentenyl-diphosphate delta-isomerase activity; protein binding; intramolecular oxidoreductase activity
Biological process: isopentenyl diphosphate metabolic process; isoprenoid biosynthetic process; dimethylallyl diphosphate biosynthetic process
Cellular component: peroxisome; cytosol
Genetic constraint (gnomAD): Loss-of-function variants: 13 observed, 12.99 expected, observed/expected ratio (o/e) 1, 90% interval 0.65 to 1.58. The upper end of that interval is the gene's LOEUF score, 1.58, which puts it in group 6 of 6, group 1 being the genes least tolerant of losing a copy. Missense variants: 307 observed, 288.09 expected, observed/expected ratio (o/e) 1.07, 90% interval 0.97 to 1.17. Synonymous variants: 131 observed, 113.26 expected, observed/expected ratio (o/e) 1.16, 90% interval 1 to 1.34.
Homologues: Orthologues: mouse Idi2 (66% identical), mouse Idi2l (66% identical), zebrafish idi1 (59% identical), tropical clawed frog idi1 (56% identical), rabbit IDI2 (53% identical), Drosophila melanogaster Idi (41% identical), Caenorhabditis elegans idi-1 (33% identical). Paralogues in human: IDI1 (65% identical).
Diseases named in the same sentence as IDI2 in open-access papers:
IDI2 is named in the same sentence as 7 diseases in open-access papers, as found by Europe PMC text mining. Sharing a sentence is not in itself a finding about the gene and the disease. The quoted sentences say what the papers report.
amyotrophic lateral sclerosis (1 paper, 2021). Amyotrophic lateral sclerosis (ALS) is a neurodegenerative disease characterized by progressive muscular paralysis reflecting degeneration of motor neurons in the primary motor cortex, corticospinal tracts, brainstem and spinal cord. "IPP is increased when the genes for the enzymes that process it like isopentenyl diphosphate isomerase 1 and 2 (IDI1 and IDI2) are disrupted in a copy number variant in amyotrophic lateral sclerosis, or when the protein is aggregated in Lewy bodies in the brain." (PMID 33735311, 2021).
Chronic tubulointerstitial nephritis (1 paper, 2024). Chronic inflammation of the kidney affecting the interstitium of the kidneys surrounding the tubules. "For the clinical types of CKD, only IDI2 was significantly associated with a decreased risk of chronic tubulointerstitial nephritis." (PMID 38898508, 2024).
prostate carcinoma (1 paper, 2020). A carcinoma that arises from epithelial cells of the prostate gland. "Genes involved in steroid synthesis included CYP21A2, HSD17B2, ITGA6, IDI2, MAP2K1, PMVK, TSPO, and may correspond to androgen dependent growth of prostate cancer." (PMID 32226005, 2020).
kidney disease (1 paper, 2025). "There were 7 proteins that exclusively associated only with the kidney domain supporting their proximal role in kidney disease (e.g., A4GALT, PCK2, EFNA3, BTN3A2, IDI2, GATM, FAIM)." (PMID 41282674, 2025).
IDI2 also shares sentences with these, for which no sentence is quoted: diabetes (1 paper); metastatic tumors (1); rhabdomyolysis (1).